SMARCA1 (SNF2 related chromatin remodeling ATPase 1)
Diseases named in the same sentence as SMARCA1 in open-access papers (continued):
Sharing a sentence is not in itself a finding about the gene and the disease.
SMARCA1 also shares sentences with these, for which no sentence is quoted: lymphoma (3 papers); rhabdoid tumor (3); chordoma (2); glioma (2); acute myeloid leukemia (1); astroblastoma (1); autism (1); bladder carcinoma (1); brain tumors (1); cervical squamous cell carcinoma (1); developmental delay (1); diffuse large B-cell lymphoma (1); endocervical adenocarcinoma (1); endometrial cancer (1); epithelioid sarcoma (1); fibrosarcoma (1); gastrointestinal tumors (1); glioblastoma (1); hematological malignancies (1); Hyperbilirubinemia (1); Infertility (1); inflammatory breast carcinoma (1); leukemia (1); lung squamous cell carcinoma (1); mesothelioma (1); osteosarcoma (1); ovarian serous cystadenocarcinoma (1); pancreatic adenocarcinoma (1); prostate adenocarcinoma (1); skin melanoma (1).
A further 10 diseases each share a sentence with SMARCA1 in 1 paper.